PIK3CA (phosphatidylinositol-4,5-bisphosphate 3-kinase catalytic subunit alpha)
Diseases named in the same sentence as PIK3CA in open-access papers (continued):
Sharing a sentence is not in itself a finding about the gene and the disease.
cancer (continued). "Phosphatidylinositol-4,5-bisphosphate 3-kinase, catalytic subunit alpha (PIK3CA) mutations that activate the PI3K/AKT signaling pathway have been observed in several types of carcinoma and have been associated with patient prognosis." (PMID 27388016, 2016). "Mucinous (8.3%) and medullary (8.8%) carcinomas had significantly fewer functional PIK3CA mutations relative to other subtypes (lobular=46.9%, mixed=50.0%, ductal=36.9%)." (PMID 27161491, 2016). "As predicted, these genetic alterations also differed from HPV-driven cancers involving the base of tongue, which had a higher frequency of activating mutations in PIK3CA, with loss of TRAF3 and amplification of E2F1." (PMID 26395002, 2015). "Mutant forms of PIK3CA, which encodes the p110a catalytic subunit, have been found in various human cancers, including colon, breast, lung cancer, and HCC, leading to increased lipid kinase activity and oncogenesis." (PMID 25826091, 2015). "In the case of cancer, for example, it is known that the two most common mutations in PIK3CA, E545K and H1047L, contribute to carcinogenesis through different mechanisms." (PMID 26485003, 2015). "In cases with wild-type KRAS, BRAF and PIK3CA a number of cancer-associated genes representing potential drivers were identified (for example, STK11, GNAS, CHEK2 and RB1)." (PMID 25855536, 2015). "Somatic activating mutations of the PI3K catalytic subunit, p110α, which is encoded by the PIK3CA gene, occur frequently in human cancers, including those of the breast, prostate, colon, and endometrium." (PMID 26125440, 2015). "Low-level PIK3CA mutations were detectable in the serum indicating the utility of cfDNA as a DNA source to detect cancer-derived mutations in metastatic biliary cancers." (PMID 26498688, 2015). "In some cases, depending on cancer cell type, PIK3CA mutation appears to show positive correlation, but PTEN loss does not." (PMID 26469692, 2015). "Conditional mouse alleles for the H1047R and E545K Pik3ca hotspot mutations have been generated to study tumor formation and assess anti-cancer activities of pathway inhibitors." (PMID 26633882, 2015). "PIK3CA is the second most commonly mutated gene across many cancer types, and was detected in more than 10% of the cancer cases examined by the TCGA." (PMID 26267324, 2015). "Because the mutated PIK3CA plays an important role in cancer cell survival, proliferation, and metabolism, PIK3CA is suggested as a therapeutic target in CRC." (PMID 26544726, 2015). "Somatic mutations in the PIK3CA gene (“hot spots” in exons 9 and 20) are found in many human cancers, and their presence can determine prognosis and a treatment strategy." (PMID 26702420, 2015). "PIK3CA mutations have been previously identified in several types of cancer, where they overactivate the PI3K/AKT/mTOR signaling in the absence of growth factors." (PMID 25915946, 2015). "One of the downstream modulators of EGFR signalling PIK3CA, exhibits activating mutations in brain metastases from breast (2/12) and other cancers (2/9)." (PMID 25969993, 2015). "The PI3K pathway is dysregulated in various cancers through either amplification or mutation in PIK3CA or inactivation of PTEN." (PMID 25834816, 2015). "For example, gain of function mutations in PIK3CA, that encodes the catalytic subunit p110α, have been detected in a wide variety of human solid cancers, whereas p110δ is implicated in cancers derived from B lymphoid cells." (PMID 25871383, 2015). "The most studied type I PI3Ks include the α, β, γ and δ subtypes; mutations or abnormal expression of PI3Kα (PIK3CA) are most commonly reported in cancer." (PMID 26267321, 2015).
cancer (continued). "On the basis of the lineage trees, we identified a large number of independent recurrences of PIK3CA H1047 mutations in separate lesions in four of the six patients, often separate from the diagnostic carcinoma." (PMID 25918554, 2015). "EBV positive carcinomas show recurrent PIK3CA mutations, extreme DNA hypermethylation, and amplification of JAK2, CD274, and PDCD1LG2." (PMID 25859432, 2015). "A CCL bearing a PIK3CA mutation was typically accompanied by wild-type carcinoma, or carcinoma with a different PIK3CA mutation (in 9 of 14 cases)." (PMID 25918554, 2015). "Activating mutations in PIK3CA have been implicated in various cancers, and occur predominantly in the helical or kinase domains of the alpha p110 catalytic subunit." (PMID 24722523, 2014). "This is consistent with the results of Meric-Bernstamet al., who reported that human cancer cells with PIK3CA and/or PTEN mutations were more likely to be sensitive to rapamycin." (PMID 24658085, 2014). "Multivariate logistic regression showed that pAKT-Thr308 levels by RPPA are significantly higher in tumors with loss of BAF250a expression (p = 0.002), those with low PTEN (p = 0.003), and cancers with activating PIK3CA mutations (p = 0.02)." (PMID 24559118, 2014). "In the multivariate Cox regression analysis, PIK3CA mutations were found to be independently associated with worse overall survival in the patients with family cancer history (multivariate HR = 10.493, 95% CI: 2.432–45.267, P = 0.002)." (PMID 25054828, 2014). "PIK3CA has been reported to be mutated frequently in human cancer,particularly in common cancer types such as breast, colorectal, endometrial andprostate." (PMID 25192370, 2014). "By combining the copious amount of sequencing data over the past year, we find that the PIK3CA gene is one of the two most commonly mutated genes identified in human cancers (the other being KRAS)." (PMID 25106743, 2014). "It indicated that the PIK3CA mutation only occurred in relatively small amount of ESCC cancer cells." (PMID 25054828, 2014). "So far there is no consensus on the most relevant predictive biomarkers for PI3K inhibitors in GBM, although there are reports demonstrating that cancers with PIK3CA mutations are most sensitive to these agents." (PMID 24718026, 2014). "Amongst these, p110α has a well-established role in cancer and gain of function of this isoform due to mutation of its gene PIK3CA is common in several human cancers." (PMID 25360116, 2014). "The class I PI3K isoform p110α has received considerable attention in oncology because the gene encoding p110α (PIK3CA) is frequently mutated in human cancer." (PMID 24915189, 2014). "While over 100 activating mutations in PIK3CA are known, mutations in two domains of the protein account for 80% of cancer-associated somatic mutations, and these same sites can be mutated in overgrowth disorders." (PMID 25513881, 2014). "Cancer cells with PIK3CA mutations have been demonstrated to acquire enhanced sensitivity to PI3K pathway inhibitors." (PMID 25054828, 2014). "The family cancer history is a risk factor for shorter overall survival for the patients with PIK3CA mutations." (PMID 25054828, 2014). "Currently early-phase and phase I clinical trials have proved higher response rate for the cancer patients with PIK3CA mutations treated with PI3K/AKT/mTOR pathway inhibitors than for those without the mutations." (PMID 25054828, 2014). "In a first study, analyzing 110 patients with CRC, Sartore-Bianchi and co-workers reported a significant resistance to EGFR-targeted therapy in the 13.6% of PIK3CA mutated cancers." (PMID 24624362, 2014).
cancer (continued). "It has been demonstrated that PI3K/Akt/mTOR is commonly deregulated in human cancers, due to the mutation of PIK3CA, Akt and phosphatase and tensin homolog (PTEN), or the loss of PTEN." (PMID 25364442, 2014). "There are reports suggesting that cancers with PIK3CA mutations are more sensitive to AKT or PI3K/mTOR inhibitors." (PMID 24705275, 2014). "Constitutively activated PI3K/Akt/mTOR signaling as a consequence of PIK3CA mutations or PTEN loss is one of the most common lesion in human cancers." (PMID 25250015, 2014). "A previous targeted study of cancer hotspot mutations also identified PIK3CA as a common mutation present in roughly half of early neoplasias, but not necessarily correlated with progression to invasive carcinoma." (PMID 24887547, 2014). "In a study which examined MBC, PIK3CA mutations were detected in 47.4% of the cancers which were aggressive and also chemoresistant." (PMID 25051360, 2014). "PIK3CA mutations were detected in 16.7% of tumors, and in the patients with mutated cancer, the regular use of aspirin was associated with a reduction of tumor specific and over all mortality of 82 and 46%, respectively." (PMID 24624362, 2014). "Activation of the PI3K pathway by deletion or inactivation of PTEN or oncogenic mutation of PIK3CA has been observed in many types of cancer as well as being implicated in drug resistance." (PMID 25566499, 2014). "Somatic gain-of-function mutations in PIK3CA are also found in a broad range of cancers (ovarian, breast, lung, stomach, colorectal, and brain)." (PMID 25513881, 2014). "There has been a report that the presence of mutations in PIK3CA, KRAS, or BRAF in CRC showed worse patient outcome, and among patients who undergo a curative resection of CRC, PIK3CA mutation is associated with shorter cancer-specific survival." (PMID 23671647, 2013). "Whole exome sequencing did not reveal secondary BRAF or RAS mutations but did demonstrate a somatic gain-of-function PIK3CA mutation (H1047R), that has previously been reported in other human cancers." (PMID 23470635, 2013). "None of the cases showed mutant allelic frequency of more than 50% suggesting that loss of the wild type PIK3CA allele or amplification of the mutant PIK3CA allele in cancer cells is exceedingly rare." (PMID 24341335, 2013). "Because the vast majority of PIK3CA gene mutations in cancer were reported in exons 9 and 20, we focused our mutation analysis on these exons." (PMID 23408974, 2013). "BGT-226 led to cell cycle arrest in the G0/G1 phase and inhibited growth in a variety of human cancer cell lines, including those that harbor the PIK3CA mutation." (PMID 24261963, 2013). "With regard to mutation frequencies, PIK3CA is the most frequently mutated oncogene in human cancers." (PMID 23768168, 2013). "Some of these mutations are considered clinically actionable, such as alterations in the PI3K pathway (loss of PTEN or PIK3R1, amplification of PIK3CA) for which targeted therapies are currently in clinical trials in several cancer types." (PMID 23441165, 2013). "The PI3K signaling pathway was brought at the center of attention in the field of cancer research by the discovery of cancer-specific gain-of-functions mutations in PIK3CA gene." (PMID 23459844, 2013). "We now present evidence that human cancer xenotumors harboring the insulin-unresponsive PIK3CA-activating mutation H1047R remain sensitive to metformin." (PMID 23986086, 2013). "One of the three lesions (lesion 1), had a somatic gain-of-function PIK3CA mutation (H1047R), that has previously been reported in other human cancers." (PMID 23470635, 2013). "PIK3CA mutations were discovered in a large-scale mutational analysis in various cancers, including 25–30% of colorectal cancers, gastric cancers and brain tumors." (PMID 23533654, 2013).
cancer (continued). "Gaining this information is important given that PIK3CA, the gene encoding human p110α, is frequently mutated in cancer and that clinical trials are under way to assess p110α as a therapeutic target in oncology." (PMID 23483710, 2013). "PIK3CA mutations were significantly more frequent in cancers from BRCAX patients (17.2%, 5/29) than BRCA2 (0%, 0/25) carriers (P = 0.030)." (PMID 23971979, 2013). "PIK3CA mutation was observed in 105 of 757 (14%) of carcinomas, characterized by location in the proximal colon (54% vs. 34%; P<0.001) and an increased frequency of KRAS mutation (48% vs. 25%; P<0.001)." (PMID 23785428, 2013). "Decreased or loss of MGMT immunohistochemical expression was found more frequently in PIK3CA-mutated carcinomas compared with PIK3CA wild-type carcinomas (35% vs. 20%, P = 0.001)." (PMID 23785428, 2013). "On the other hand, only exon 20 PIK3CA-mutated carcinomas were more frequently MSI-high than PIK3CA wild-type carcinomas (30% vs. 12%; P = 0.005)." (PMID 23785428, 2013). "The overall mutation frequency of KRAS, BRAF and PIK3CA in our HNSCC samples was lower than reported for other cancers." (PMID 22994622, 2012). "This population was selected based on the higher antitumor activity observed in preclinical models with PIK3CA mutations or amplifications using the Cancer Cell Line Encyclopedia." (PMID 23232172, 2012). "Activating mutations and genomic amplifications of the PIK3CA gene have been found also in many other human cancers." (PMID 23185308, 2012). "To the best of our knowledge, we demonstrated for the first time a high prevalence of somatic missense mutations (23.2%) in the PIK3CA gene in human BP-NETs that is comparable to the mutational frequency of the PIK3CA gene in other types of human cancers." (PMID 22949056, 2012). "Some single nucleotide polymorphisms (SNP) in various exons of the PIK3CA gene have also been found although their functional significance in human cancer is unclear." (PMID 23185308, 2012). "PIK3CA mutations and amplification are two major causes of overactivation of this pathway in human cancers." (PMID 22292935, 2012). "Among the catalytic subunits, p110α, encoded by the PIK3CA gene has been shown to be mutated and activated in many human cancers." (PMID 22666336, 2012). "Several studies provided evidence to suggest that cancer cells harboring PIK3CA gain-of-function mutations are selectively sensitive to inhibitors of different components of the PI3K pathway." (PMID 22970424, 2012). "Mutations in exons 9 and 20 of PIK3CA were found in three specimens (2.6%), and these mutations are known to be hotspot mutations that generate a constitutively active kinase in other cancers." (PMID 22994622, 2012). "Among the four different isoforms of the p110 catalytic subunit of PI3K, PIK3CA, the gene encoding the p110α catalytic subunit, is the only gene frequently mutated in cancer; these mutations occur in the helical or kinase domains of the catalytic subunit." (PMID 22928112, 2012). "Cell lines harboring activating mutations of the PIK3CA gene were more sensitive than wild-type PIK3CA cancer cell lines." (PMID 24281308, 2012). "The PIK3CA gene is one of the best studied oncogenes, and is amplified, overexpressed, or frequently mutated in many cancers, including GC." (PMID 22876838, 2012). "PIK3CA is frequently mutated in certain cancers such as: breast, ovarian, colorectal, endometrial and lung although its role as a driver mutation in these cancers remains controversial." (PMID 23006971, 2012). "Of the six cases where biopsies were positive for cancer cells, three showed PIK3CA mutations (one heterozygous E545 K mutation, one heterozygous H1047R heterozygous mutation, and one H1047R apparent heterozygous mutation)." (PMID 22970388, 2012).
cancer (continued). "Dependence on glucose for growth was also shown across a wider panel of cancer cell lines harbouring endogenous PIK3CA mutations." (PMID 23028762, 2012). "PIK3CA alterations have been associated with cancer recurrence, metastasis, and poor prognosis in a variety of human cancers." (PMID 22666248, 2012). "The mutation frequency in carcinomas for PIK3CA varies between 10–30% and mostly affects exons 9 and 20 (both completely covered in our analysis)." (PMID 22848674, 2012). "Activating mutations in the gene encoding for p110 (PIK3CA), a catalytic subunit of Class IA PI3Ks, have been found in many different types of human cancer." (PMID 21439058, 2011). "PI3Kα is closely involved in tumorigenesis since a high frequency of mutations in, and amplifications of the PIK3CA gene which encodes p110α, has been found in human cancers." (PMID 21694679, 2011). "The presence of activating mutations in PIK3CA specifically in GBC has clinical implications in both the diagnosis of this cancer type, as well as the potential utility of targeted therapies such as PI3 kinase inhibitors." (PMID 21303542, 2011). "A total of 504 patients with diverse advanced cancers were analyzed for the presence of PIK3CA mutations." (PMID 21829508, 2011). "The PIK3CA (phosphatidylinositol 3-kinase, catalytic, α-polypeptide) gene that encodes p110α is frequently mutated in many human cancers, including CRC." (PMID 21966435, 2011). "Mutations of the PIK3CA gene were found with high frequency in colon, brain, breast, liver, and gastric cancers suggesting an involvement of isoform p110α in cancer." (PMID 22046194, 2011). "PIK3CA mutations were observed in 7% of cancers and were more frequent in CRCs in females (p = 0.04)." (PMID 21473780, 2011). "Cancers containing PIK3CA mutations are often sensitive to the mTOR inhibitor rapamycin and the modified rapamycins (Rapalogs)." (PMID 21411864, 2011). "Recently, a key role as oncogene is emerging for PIK3CA, as it is one of the genes most frequently hit by somatic mutations in several types of human cancer." (PMID 20398348, 2010). "These events include CDKN2A deletion and MYC amplification in immortalization, HRAS activation in transformation, PIK3CA activation in the formation of malignant tumors, and RUNX1 deletion associated with poorly-differentiated malignant tumors." (PMID 20169162, 2010). "PIK3CA is one of the genes most frequently mutated in human cancers and it is a potential target for personalized therapy." (PMID 20398348, 2010). "The highest frequency of activating mutations of PIK3CA gene has particularly been found in breast and colorectal cancers." (PMID 20804548, 2010). "The incidence rates of these mutations indicate that PIK3CA is one out of the two most commonly mutated genes, identified in human cancers (the other one being KRAS)." (PMID 20804548, 2010). "Further, these non-Akt dependent effectors of PI3K signaling, such as SGK3, can promote cancer in the presence of PIK3CA mutations." (PMID 21317449, 2010). "The lack of association with any clinical-pathological condition suggests that mutations in PIK3CA occur early in the development of cancer." (PMID 20398348, 2010). "PIK3CA H1047L is an activating mutation in a well-studied gene with many known activating mutations that result in cancer." (PMID 20011534, 2009). "PIK3CA is a well-known oncogene and H1047L is in a known cancer-associated mutation hotspot within the kinase domain." (PMID 20011534, 2009). "Inactivating mutation of PTEN and activating mutation of PIK3CA have been detected in many human cancers and have been known as major activating mechanisms of AKT-signalling pathway in cancers." (PMID 18392055, 2008). "The PTEN-PIK3CA-AKT signalling cascade is frequently deregulated in several types of cancers and expression of PIK3CA has been strongly associated with elevated AKT activity." (PMID 18405350, 2008).